AKR1B10 (aldo-keto reductase family 1 member B10)
Diseases named in the same sentence as AKR1B10 in open-access papers (continued):
Sharing a sentence is not in itself a finding about the gene and the disease.
colorectal cancer (25 papers, 2014 to 2025). A primary or metastatic malignant neoplasm that affects the colon or rectum. "Loss of AKR1B10 in colorectal cancer drives metastasis by disrupting PP2A-mediated c-Myc inactivation." (PMID 40845116, 2025). "AKR1B8 deficient mice are highly susceptible to DSS-induced colitis and colitis-associated tumorigenesis, suggesting the etiopathogenic role of AKR1B10 deficiency in UC and associated colorectal cancer." (PMID 38370384, 2024). "UC is a predisposing condition with high risk of developing colorectal cancer 4; acrolein-protein lesions and DNA damage are increased in AKR1B10 silencing cells and in UC tissues with AKR1B10 deficiency." (PMID 38370384, 2024). "Acrolein is a risk factor of colorectal cancer and AKR1B10 catalyzes reduction of acrolein to a less cytotoxic alcoholic form 42-44." (PMID 38370384, 2024). "An increased AKR1B10 expression was associated with a poorer prognosis in oral squamous cells, gastric carcinomas, and lung adenocarcinomas whereas a decreased AKR1B10 expression was associated with a significantly worse survival in colorectal cancer." (PMID 35159076, 2022). "Aldo-keto reductase 1B10 (AKR1B10) is downregulated in human ulcerative colitis (UC) and colorectal cancer, being a potential pathogenic factor of these diseases." (PMID 33644071, 2021). "Subsequent analysis of sera of healthy donors and colon cancer patients revealed a strong and reproducible decrease in the AKR1B10 mRNA abundance in patients' sera, which implies that this mRNA is a promising diagnostic marker of colorectal cancer." (PMID 31413744, 2019). "Additionally, it has been shown that loss of AKR1B10 promotes the proliferation and migration of colorectal cancer cells via activation of fibroblast growth factor 1 (FGF1)." (PMID 35204145, 2022). "Data in microarray datasets (GSE39582) showed that AKR1B10 expression decreased in colon adenocarcinomas at all stages, and low expression of AKR1B10 was associated with reduced survival rate, being a potential prognostic marker in colorectal cancer." (PMID 33644071, 2021). "AKR1B10 was downregulated in 87.79% of colorectal cancer (undetectable in 63.13% cases and diminished in 24.66%), which is consistent with literature reports 37-39." (PMID 38370384, 2024). "This study evaluated AKR1B10 expression in colorectal cancer using a tissue microarray that contained 619 cases with complete pathological and follow-up data of 25 years." (PMID 38370384, 2024). "This study evaluated AKR1B10 expression in 592 colorectal cancer cases with a mean follow-up of 25 years and evaluated its potential role in development and prognosis of colorectal cancer." (PMID 38370384, 2024). "This study extensively evaluated the expression and prognostic value of AKR1B10 in a cohort of 592 colorectal cancer cases with a mean follow-up of 25 years." (PMID 38370384, 2024). "AKR1B10 was reported to suppress tumor development and progression in colorectal cancer and gastric cancer, but remains controversial in nasopharyngeal cancer and esophageal cancer." (PMID 39712017, 2024). "Aldo-keto reductase 1B10 (AKR1B10) protein is primarily expressed in intestinal epithelial cells, but lost in colorectal cancer tissues." (PMID 38370384, 2024). "Using a tissue microarray, we investigated the expression of AKR1B10 in tumor tissues of 592 colorectal cancer patients with a mean follow-up of 25 years." (PMID 38370384, 2024).
colorectal cancer (continued). "AKR1B10 expression is remarkably downregulated in colorectal cancer, and its low expression is highly correlated with the unfavorable prognosis of patients with colorectal cancer." (PMID 37884970, 2023). "mRNAs that encoded the all-trans retinaldehyde-reducing enzymes RDH11 and AKR1B10 were present in normal colorectal cells, and AKR1B10 mRNA was the most abundant and reduced in colorectal cancer samples." (PMID 37569466, 2023). "The decreased level of AKR1B1 was reported to be involved in small percent of colorectal cancer, whereas decreased expression of AKR1B10 was found in most of colorectal cancer samples." (PMID 35178443, 2022). "Nevertheless, it is reported that compared with adjacent normal colorectal tissues, AKR1B10 in colorectal cancer (CRC) tissue is down-regulated and is related to the patient’s clinic pathological conditions." (PMID 34027794, 2021). "The expression of selected genes related to MG degradation III (AKR1B10, AKR1C2 and ADH4), glyoxalase system (GLO1 and HAGH), glucose transport (SLC2A1 and SLC5A1) and colorectal cancer-associated genes (AREG, CXCL8 and CEACAM1) were quantitated using qRT-PCR." (PMID 32561807, 2020). "However, it is a different scenario in the intestine, where AKR1B10 is normally expressed, but undetectable or markedly diminished in UC, Crohn's disease and colorectal cancer tissues 37-39." (PMID 38370384, 2024). "Our data proposed a novel paradigm of AKR1B10 in colorectal cancer." (PMID 38370384, 2024). "We then evaluated whether AKR1B10 expression in colorectal cancer tissues was correlated with tumor growth and progression." (PMID 38370384, 2024). "Additionally, AKR1B10-gene silencing results in the inhibition of colorectal cancer cell growth, suggesting that AKR1B10 regulates cell proliferation." (PMID 24348813, 2014). "Thus, the downregulation of AKR1B10 in the colon may be a contributing factor to the development of colorectal cancer." (PMID 35204145, 2022). "In addition, AKR1B10 knock-down resulted in the inhibition of apoptosis in colorectal cancer cells." (PMID 33968341, 2021). "Here, we identify aldo-keto reductase family 1 member B10 (AKR1B10), down-regulated in gastrointestinal cancers, as a pivotal metastasis suppressor correlating with improved colorectal cancer (CRC) prognosis." (PMID 40845116, 2025). "In colorectal carcinoma, the AKR1B1 and AKR1B10 expression levels in tumor cells, both AKR family members, and their effect on the proliferation ability of tumor cells showed opposite trends." (PMID 37751590, 2023). "Taken altogether, our results suggest that AKR1B10 expression in colorectal cancer tissues has not any prognostic values." (PMID 38370384, 2024). "AKR1B10 expression was not correlated to the overall survival and disease-free survival of this cohort of colorectal cancer patients." (PMID 38370384, 2024). "Together this study suggests that AKR1B10 downregulation may not be a prognostic but a carcinogenic factor of colorectal cancer." (PMID 38370384, 2024). "In mice, targeted deficiency of AKR1B8 (an orthologue of human AKR1B10) leads to high susceptibility to dextran sulfate sodium (DSS)-induced colitis and associated colorectal tumorigenesis 39; in humans, AKR1B10 was reported as a negative prognostic marker of colorectal cancer." (PMID 38370384, 2024). "Therefore, AKR1B10 downregulation in colorectal cancer may not be a prognostic factor, but an early event and carcinogenic driver in colorectal carcinogenesis." (PMID 38370384, 2024).
gastric cancer (20 papers, 2013 to 2025). A primary or metastatic malignant neoplasm involving the stomach. "This study also takes gastric cancer as a role model to examine the AKR1B10 expression and its association with TME." (PMID 39712017, 2024). "The later was challenges by a recent report in which AKR1B10 was expressed in 58.5% gastric cancer and associated with a poor 5-years overall survival." (PMID 35280770, 2022). "A study on patients with gastric cancer who underwent neoadjuvant chemotherapy showed that high AKR1B10 expression was associated with lymph node metastasis and a poor response to neoadjuvant chemotherapy." (PMID 34063865, 2021). "In contrast to AKR1B1, AKR1B10 expression was significantly decreased in gastric cancer and associated with tumor size, stage, and metastasis, suggesting that AKR1B10 may be a reliable prognostic indicator." (PMID 39055885, 2024). "AKR1B10 has been identified as a tumor proliferation and metastasis marker in multiple tumors, for example, AKR1B10 expression is predictive of the treatment response of locally advanced stomach cancer, and its expression is associated with poor prognosis and lymph node metastasis." (PMID 37884970, 2023). "exhibit that high AKR1B10 is correlated with high metastasis, tumor progression, poor responses to chemotherapy and low survival rate in gastric cancer." (PMID 39712017, 2024). "It is possible that AKR1B10 is important for the gastric cancer development, and relate to macrophage infiltration." (PMID 39712017, 2024). "Considering the essential biological function of AKR1B10 and its downregulation in gastric cancer, we would like to consider AKR1B10 as a protective factor in normal gastric tissues." (PMID 39712017, 2024). "The results showed that AKR1B10 expression was dramatically decreased in gastric cancer compared to normal tissues." (PMID 39712017, 2024). "We evaluated AKR1B10 expression in paired normal and gastric cancer tissues, and the correlation of AKR1B10 expression with immune cells in gastric cancer." (PMID 39712017, 2024). "The expression of AKR1B10 and immune cell markers in gastric cancer were evaluated with multiplex immunofluorescence staining." (PMID 39712017, 2024). "This study particularly revealed the diminished expression of AKR1B10 in gastric cancer, and discussed the potential role of AKR1B10 in the gastric cancer TME." (PMID 39712017, 2024). "This study integrated the sequencing data of 33 cancer types, including gastric cancer, from TCGA project to explored the expression pattern and genetic and epigenetic alterations of AKR1B10." (PMID 39712017, 2024). "This study verified AKR1B10 expression and immune infiltration in gastric cancer, and our results consistently demonstrated that AKR1B10 expression was diminished in gastric cancer accompanied with CD19+ B cell proportion decline and CD68+ macrophage increase." (PMID 39712017, 2024). "The study tended to delineate the role and regulatory mechanism of aldo-keto reductase 1B10 (AKR1B10) in gastric cancer progression." (PMID 37823316, 2023). "The relationship of AKR1B10 expression with survival rate in gastric cancer was analyzed through Kaplan–Meier analysis." (PMID 37823316, 2023). "Our results indicated that AKR1B10 inhibited migration, invasion, and adhesion of gastric cancer cells via modulation of ITGA5." (PMID 37823316, 2023). "Via rescue experiments, it was concluded that AKR1B10 served as tumor suppressor potentially by ITGA5 expression in gastric cancer." (PMID 37823316, 2023). "Overexpressing AKR1B10 hindered gastric cancer cell proliferation, migration, invasion and adhesion." (PMID 37823316, 2023). "The results unveiled that integrin subunit alpha 5 was upregulated, while AKR1B10 was downregulated in gastric cancer tissues and cells." (PMID 37823316, 2023). "Aldo–keto reductase family 1 member B10 (AKR1B10) is associated with several cancers, but the prognostic role in gastric cancer (GC) remains unclear." (PMID 36661656, 2022).
gastric cancer (continued). "AKR1B10 has been shown to be closely related to tumor size and cell metastasis of gastric cancer, and AKR1B10 can be used as a good prognostic indicator for gastric cancer." (PMID 31341536, 2019). "As AKR1B10 expression almost diminished in gastric cancer, we evaluated the relationship between AKR1B10 and immunity by dividing samples with AKR1B10 expression into AKR1B10 high group with H score > 10, AKR1B10 medium group with 10 > H score > 0.5 and AKR1B10 low group with H score < 0.5." (PMID 39712017, 2024). "In addition, the overexpression of AKR1B10 in gastric cancer MKN46 cells stimulates migration and down-regulates peroxisome proliferator-activated receptor-γ (PPARγ) that is closely linked to growth suppression and death of cancer cells." (PMID 34063865, 2021). "Furthermore, AKR1B10 is now established as a promising cancer target (except for gastric cancers, where it is downregulated), and the ubiquitously expressed AR can represent a problematic off-target, given its overall similarity with AKR1B10." (PMID 34940623, 2021). "A poor prognosis in gastric cancer is suggested by the down-regulation of AKR1B10 expression." (PMID 34063865, 2021). "Similarly, Yao and colleagues found AKR1B10 down-regulation in gastric cancer compared with paired normal mucosa, contrary to what was found by Kropotova and colleagues." (PMID 32012980, 2020). "In addition, AKR1B10 may provoke pancreatic cancer through mediation of K-Ras protein prenylation and cell apoptosis, but in gastric cancer, AKR1B10 was reported as a favorable prognostic marker." (PMID 35280770, 2022). "The sedative propofol reduced the proliferation of BGC823 and GES-1 gastric cancer cells by significantly decreasing the expression of both AKR1B1 and AKR1B10 via the NRF2-mediated polyol pathway." (PMID 39055885, 2024). "While the expression levels of AKR1B10, AKR1C1, AKR1C2, and AKR7A3 were significantly low in gastric cancer tissues, AKR6A5 expression was higher relative to normal tissues." (PMID 39055885, 2024). "In the stomach, along with the diminishing of AKR1B10 expression, CD68+ macrophage increased and CD19+ B cell decreased in gastric cancer." (PMID 39712017, 2024). "The mRNA levels of AKR1B10 and integrin subunit alpha 5 (ITGA5) in gastric cancer tissues and cell lines were measured by real-time quantitative polymerase chain reaction." (PMID 37823316, 2023). "Clinical and basic research has proven that AKR1B10 is down-regulated in gastrointestinal cancers and several inflammatory bowel diseases, proposing that its low expression is correlated with poor prognosis and decreased survival for patients with CRC and gastric cancer." (PMID 34063865, 2021).
pancreatic cancer (19 papers, 2014 to 2025). "AKR1B10 expression is upregulated and has been proposed as a prognostic biomarker in breast and pancreatic cancer types." (PMID 39001490, 2024). "Previous study had demonstrated that OA was the most potent AKR1B10 competitive inhibitor, which was used in pancreatic cancer to inhibit the AKR1B10 activity, and thereby suppressed cell growth in vitro and in vivo." (PMID 34035231, 2021). "Studies have shown that AKR1B10 can induce a variety of cancers, such as liver cancer, non-small cell lung cancer, and pancreatic cancer, and represents a promising potential cancer target." (PMID 34150630, 2021). "The role of AKR1B10 in modulating the Kras-E-cadherin pathway is further supported by the overexpression, knockdown, and inhibition of the enzyme in pancreatic cancer CD18/HPAF and Panc10.05 cells and xenograft tumors." (PMID 34063865, 2021). "Inhibition of AKR1B10 constrains the growth of pancreatic cancer through modulation of the KRAS-E-cadherin pathway." (PMID 30320113, 2018). "Inhibition of AKR1B10 prevents the outgrowth of pancreatic carcinoma cells by modulating the Ras pathway." (PMID 27562730, 2016). "Similarly, AKR1B10 activates K-Ras mediated MEK/ERK signaling activity in pancreatic cancer." (PMID 38370384, 2024). "AKR1B10 is thought to increase the prenylation of Ras protein that is critical in OSCC, as described in the pancreatic cancer section (Section 6.5)." (PMID 34063865, 2021). "Studies have shown that AKR1B10 can induce a variety of cancers, such as HCC, non-small cell lung cancer, and pancreatic cancer, and is a promising potential cancer target." (PMID 36814910, 2023).
liver cancer (18 papers, 2014 to 2026). An epithelial or non-epithelial malignant neoplasm that arises from the liver. "A meta-analysis of five studies including 798 patients demonstrated that high AKR1B10 expression in liver malignant tumor was associated with better overall survival in patients with HCC after hepatectomy (HR = 0.54, 95% CI: 0.41–0.72, p < 0.001)." (PMID 36584078, 2022). "Given that AKR1B10 is a validated secretory protein detectable by commercial ELISA kits, and its secreted levels serve as a prognostic indicator in liver cancer, investigating the effect of lactylation on its secretion warrants future research." (PMID 41454479, 2026). "AKR1B10 influences liver cancer cell proliferation and apoptosis by regulating the glycolytic pathway." (PMID 40777026, 2025). "AKR1B10 is upregulated by EGF and insulin through AP-1 signaling and is associated with the development of liver cancer." (PMID 39001490, 2024). "Many experimental studies also proved AKR1B10 role in the pathogenesis of liver cancer, development, and resistance to chemotherapeutic drugs." (PMID 37884970, 2023). "In liver cancer, AKR1B10 mediates the proliferation of liver cancer cells through sphingosine-1-phosphate." (PMID 35602603, 2022). "Consistent with the transcriptomic analyses, many proteomic studies also indicated very significant elevations in the protein expression of AR and AKR1B10 in human liver cancer tissues." (PMID 28978011, 2017). "Zopolrestat, an AR/AKR1B10 inhibitor, was found to provide additional therapeutic effects in liver cancer." (PMID 28978011, 2017). "AKR1B10 has been reported as an effective biomarker of advanced liver fibrosis and liver cancer." (PMID 36119721, 2022). "Furthermore, 1000 lasso analysis also identified five genes: ADH4, AKR1B10, CEBPZOS, ENO1, and FOXN2, as the most stable prognosis-related genes associated with energy metabolism in liver cancer." (PMID 35602603, 2022). "In summary, we found that AKR1B10 is involved in cell proliferation of liver cancer through S1P." (PMID 26948042, 2016). "Based on the marker genes of this cluster and TCGA database data, the five most stable key genes (ADH4, AKR1B10, CEBPZOS, ENO1, and FOXN2) were identified as energy metabolism-related genes in liver cancer." (PMID 35602603, 2022). "Of note, AKR1B10, ACSL4, GLS2, LCAT, were among the metabolic targets we previously identified as consistent in HCC, indicating a high alteration frequency of these genes across liver cancer datasets." (PMID 30176945, 2018).